CSPG4 (chondroitin sulfate proteoglycan 4)
Diseases named in the same sentence as CSPG4 in open-access papers (continued):
Sharing a sentence is not in itself a finding about the gene and the disease.
type I hypersensitivity (1 paper, 2023). An inflammatory response driven by antigen recognition by antibodies bound to Fc receptors on mast cells or basophils, occurring within minutes after exposure of a sensitized individual to the antigen, and leading to the release of a variety of inflammatory mediators such as histamines. "To gain preliminary insights of the perceived risk of type I hypersensitivity associated with IgE, we asked whether CSPG4 IgE could potentiate degranulation of patient-derived circulating basophils." (PMID 37185332, 2023).
tumor (188 papers, 2006 to 2026). "Chondroitin sulfate proteoglycan-4 (CSPG4) serves as an early cell surface marker of tumor progression and is linked to enhanced migration, invasion, and proliferation of tumor cells." (PMID 40284831, 2025). "Chondroitin sulfate proteoglycan 4 (encoded by CSPG4), a cell surface proteoglycan, plays multiple roles in tumor growth and metastasis." (PMID 38808892, 2024). "Many studies have revealed that anti-CSPG4 monoclonal antibodies or lentiviruses encoding a CSPG4-targeted shRNA in tumors restricted tumor growth and metastasis." (PMID 38338902, 2024). "Downregulation of CSPG4 was significantly associated with decreased tumor burden and peritoneal metastasis." (PMID 38338902, 2024). "Bortezomib, as a chemotherapy agent, can trigger immunogenic cell death, thereby promoting anti-tumor immunity, and our candidate antigen, CSPG4, was strongly associated with Bortezomib." (PMID 37854594, 2023). "CSPG4 plays an important role in the growth and survival of tumor cells, and overexpression of CSPG4 has been associated with recurrent metastasis of cancer." (PMID 37872487, 2023). "The CSPG4 is also expressed in cancer-associated fibroblasts and a subpopulation of stromal cells with a role in tumor invasion and growth." (PMID 36768830, 2023). "We also demonstrated that CSPG4 IgE increased macrophage tumor infiltration and associated with activation of several pro-inflammatory immune pathways." (PMID 37185332, 2023). "As mentioned, three genes were mutated exclusively in pre-NACT tumor samples of resistant cases (CSPG4, TUBA3D, SLC35G5)." (PMID 35501919, 2022). "CSPG4 is a cell surface proteoglycan, considered as an ideal tumor-associated antigen, that is, an oncoantigen." (PMID 35480887, 2022). "Purified IgEs specific for the tumor-associated antigens Chondroitin Sulfate Proteoglycan 4 (CSPG4-IgE) and Human Epidermal Growth Factor Receptor 2 (HER2-IgE) were devoid of by-products such as free light chains." (PMID 36362241, 2022). "Recently, a variation in the human CSPG4 gene has been shown to increase susceptibility to the Neurofibromatosis type 1-like phenotype, a phenomenon linked to the appearance of benign tumours and growths on nerves." (PMID 36428658, 2022). "In order to generally mitigate the risk for potential on-target/off-tumor toxicity associated with targeting CSPG4, our group has developed the generation of CSPG4-specific CAR-T cells via mRNA-electroporation." (PMID 36291817, 2022). "CSPG4 expression is clearly linked to malignancy in tumour cells, however, what this model shows is that understanding how dynamic changes in CSPG4 expression can be used for clinical diagnosis will be challenging." (PMID 36428658, 2022). "CSPG4 monoclonal antibodies can cause a blockade of migratory, mitogenic and survival signalling pathways in tumor cells, making CSPG4 a new TNBC target." (PMID 32245065, 2020). "Various reports have described CSPG4 expression in pericytes surrounding tumor-associated endothelial cells." (PMID 31779130, 2019). "A soluble NG2/CSPG4 fragment released from tumor cells or tumor-associated pericytes can stimulate endothelial cell migration in the tumor microenvironment by interacting with galectin-3 and α3β1 integrin on the endothelial surface." (PMID 30213051, 2018). "Preclinical models revealed that T cells transfected with RNA (e.g., encoding mesothelin-, CD19-, or chondroitin sulfate proteoglycan 4 (CSPG4)-specific CARs) showed anti-tumor effects in vitro and in vivo." (PMID 30103488, 2018). "Here we review various methods of exploiting tumor-associated CSPG4 expression to improve targeted cancer therapy." (PMID 28657611, 2017).
tumor (continued). "CSPG4 over-expression has also been involved in cancer cell progression through the regulation of intracellular pathways implicated in tumor cell adhesion and migration." (PMID 28668095, 2017). "Galectin-3, a lectin family member strongly associated with tumor metastasis, has been shown to form a complex with α4β1 integrin and CSPG4." (PMID 28657611, 2017). "This tumor-associated overexpression of CSPG4 points towards a highly promising therapeutic target for antibody-guided cancer therapy." (PMID 28657611, 2017). "Our data show for the first time that P-selectin can bind to tumor cells via CSPG4 and that CHST11 expression is linked to P-selectin-reactive cell surface CS/DS-GAGs." (PMID 21658254, 2011). "Furthermore, overcoming the therapeutic limitation posed by TSA heterogeneity and tumour escape via loss of cell surface antigen has been considered by targeting multiple MAAs (e.g., CSPG4 alongside tyrosinase-related protein 1)." (PMID 39409881, 2024). "Based on these findings that implicate the importance of CSPG4 for tumors proficient in its expression, researchers have proposed that it is very unlikely for tumor cells to undertake mechanisms for CSPG4 down-regulation and/or loss following its targeting via CAR-Ts." (PMID 38146364, 2023). "In addition, CSPG4 is a dominant tumor-associated antigen that is also involved in normal-tissue development in humans." (PMID 36768830, 2023). "Likewise, the reprogrammed CSPG4 CAR T cell (RP-CSPG4 CAR T cell) treatment caused complete tumor regression of orthotopic TNBC SUM149 cell line-derived solid tumors in 100% of mice." (PMID 37714830, 2023). "Finally, we examined the correlation between CSPG4 and clinicopathological factors in patients with BLCA and identified an association between CSPG4 and tumor stage." (PMID 38015710, 2023). "In addition, CSPG4 expression was found on cancer-associated vasculature, which would render the tumor microenvironment sensitive to CSPG4-directed CAR-T cells." (PMID 36291817, 2022). "Moreover, several studies have linked CSPG4 expression to the development of certain cellular traits necessary for tumour progression." (PMID 36428658, 2022). "In addition, CSPG4 has been found to be expressed on tumor-associated pericytes, and to a significantly lower level on normal resting pericytes." (PMID 36291817, 2022). "Multiple HSPGs and CSPGs core proteins and related enzymes were upregulated in GBM tumors relative to normal brain, including various genes previously implicated in tumor invasion and tumorigenesis and observed by the present study, including glypican 1, CSPG4, BGN, and AGRN." (PMID 35202840, 2022). "In this study, we use radionuclide molecular imaging, for the first time, to compare the trafficking and biodistribution of two engineered homologous IgG and IgE antibodies targeting a tumor-associated antigen, CSPG4 (chondroitin sulfate proteoglycan 4): anti-CSPG4 IgG and anti-CSPG4 IgE." (PMID 34513315, 2021). "However, CSPG4 has been suggested to be less prone to antigen loss during CAR-T-cell therapy, consistent with our findings that residual tumor cells remain susceptible to anti-CSPG4-PDD treatment." (PMID 32331483, 2020). "In patients with a high metastatic burden in the central nervous system, the use of CSPG4-CAR-T cells might entail the risk of causing acute cerebral hemorrhage by eliminating tumor-associated vasculature." (PMID 31779130, 2019). "Regarding CSPG4 presence on pericytes, it could be demonstrated that CSPG4 is significantly higher expressed in tumor-associated activated pericytes as compared to normal resting pericytes." (PMID 31779130, 2019). "Interestingly, TNF-α released by tumor-associated microglia further induced CSPG4 expression in the GB cells." (PMID 31798595, 2019). "It remains unclear whether CSPG4 has a role in tumor initiation or its expression only accumulates in tumors as a secondary tumor-associated event." (PMID 29375561, 2017).
tumor (continued). "Our team recently demonstrated that combination treatment with NK cells +mAb9.2.27 against the NG2/CSPG4 proteoglycan diminished tumor growth that was associated with reduced tumor proliferation, increased cellular apoptosis and prolonged survival compared to vehicle and monotherapy controls." (PMID 24085644, 2014). "Given that these three molecules are implicated in partially overlapping yet distinct aspects of tumor progression, a combinatorial therapeutic strategy that simultaneously targets CSPG4, xCT, and TLR2 may represent a novel and more effective approach to disrupt multiple tumor-supportive mechanisms." (PMID 41375047, 2025). "However, anti-CSPG4 TCRs may be more susceptible to on-target/off-tumour toxicities than their CAR T cell counterparts." (PMID 39409881, 2024). "Hence, these CSC attributes could partially explain the discrepancy in CSPG4 expression status in these different cell lines, as this phenotype is strongly associated with different tumor growth phases and poor prognosis." (PMID 37432459, 2023). "Thus, CAR-T cells generated via mRNA-electroporation could mitigate the risk for inadvertent on-target/off-tumor targeting when targeting decitabine-upregulated CSPG4." (PMID 36291817, 2022). "Notably, studies using CSPG4 as a marker for circulating tumour cells, which may provide cellular context, have yet to be conducted, and future work in this area will shed further light on the utility of CSPG4 as a diagnostic blood marker." (PMID 36428658, 2022). "Therefore, we produced an antibody recognizing the tumor-associated antigen CSPG4, as this cell surface neural crest antigen is over-expressed in a large proportion (~70–80%) of melanotic and other solid tumors, and it is found on cells likely to confer an aggressive phenotype." (PMID 32331483, 2020). "Albeit we tried to selectively study tumour‐derived EVs using either capturing with CSPG4‐antibody conjugated beads or by analysing the presence of EGFR T790M mutation in RNA in the EVs, we did not manage those verifications at this point." (PMID 41581122, 2026). "This ADC was capable of robust internalisation into cancer cells and tumour cell cytotoxicity in vitro, and significant growth restriction of two CSPG4-expressing TNBC patient-derived xenografts (PDX) implanted orthotopically in mouse mammary fat pads." (PMID 41794948, 2026). "Given this, it would be interesting to compare CSPG4 levels in EGFR mutant tumours and their released EVs with samples from EGFR‐TKI treatment‐naïve patients at baseline and upon progression." (PMID 41581122, 2026). "Recently, CSPG4-specific chimeric antigen receptors (CARs) have been developed and tested preclinically, demonstrating striking efficacy in controlling tumor growth in human xenografts." (PMID 41375047, 2025). "We observed that CSPG4 CAR T cells were able to significantly control tumor growth compared to control groups, as demonstrated by macroscopical observation, as well as by a significant reduction of tumor weight." (PMID 40847369, 2025). "In the relma-cel study, the expression levels of tumor-associated fibroblast markers (AP, TNC, CSPG4, PDGFRA, S100A4, ASPN, STC1, and ITGAM) were higher in the patients with PR than with CR." (PMID 39858099, 2025). "A slight, but not significant decrease in the mean killing efficacy was observed after SPION‐loading, especially in tumor cells with medium CSPG4 expression." (PMID 39764559, 2025). "On the other hand, CSPG4 CAR T cells mediated complete tumor eradication only in 2/5 mice and partially controlled tumor growth in 3/5 mice." (PMID 40847369, 2025). "After four days, FACS analysis demonstrated that CSPG4.CAR-T cells significantly eliminated tumor cells compared to CD3-NTs." (PMID 40724839, 2025). "These analyses revealed significantly higher CSPG4 transcript abundance in a majority of malignant tumor cells from patient samples compared to healthy skin cells, including melanocytes." (PMID 40082557, 2025).
tumor (continued). "Chondroitin sulfate proteoglycan 4(CSPG4), a transmembrane protein, is aberrantly expressed in various cancers and has been implicated in tumor invasion and lymphovascular infiltration." (PMID 40908816, 2025). "CSPG4 has been reported to promote tumor growth and survival through numerous signaling pathways associated with its extracellular domains." (PMID 40082557, 2025). "PANO tumor also had higher expression of CSPG4, and K-M analysis validated that high-expression tumors had shorter OS in BLCA." (PMID 40918470, 2025). "Preclinical studies have shown that CSPG4-targeted CAR-T cells can effectively reduce tumor burden, demonstrating strong cytotoxicity against CSPG4-positive tumor cells even in high-antigen-density environments." (PMID 40724839, 2025). "CSPG4 promotes tumor cell adhesion, proliferation, migration, and resistance to therapy through its interactions with the ECM and the regulation of key signaling pathways." (PMID 41375047, 2025). "These Fc-mediated functions align with findings generated with other tumor-antigen specific IgE antibodies, including those targeting FRα and CSPG4." (PMID 39934835, 2025). "This approach deserves further investigation taking into account that even active immunization strategies against CSPG4 are in development and are effective in deferring tumor growth and metastasis in osteosarcoma preclinical models." (PMID 40004005, 2025). "For instance, B7-H3/CSPG4-targeted DT CAR-T cells demonstrated robust antitumor activity in desmoplastic breast tumors by simultaneously targeting tumor and stromal components, thereby reducing ECM density and improving intratumoral infiltration." (PMID 41348261, 2025). "CSPG4 is a transmembrane proteoglycan, highly expressed in different tumor histotypes, while barely present in healthy tissues, where its expression is generally restricted to precursor or progenitor cells, whilst absent in terminally differentiated cells." (PMID 41375047, 2025). "In our previous studies we have demonstrated that the tumor antigens B7-H3 and CSPG4 are highly and homogeneously expressed in different types of solid tumors, with limited distribution on normal tissues." (PMID 40847369, 2025). "The different activation thresholds explain the observed divergence between lysis and cytokine release toward CSPG4‐expressing tumor cells, with continued tumor cells lysis, while cytokine secretion was diminished." (PMID 39764559, 2025). "For instance, TYRP1-directed CAR T cells effectively controlled tumor growth in xenograft models, and CSPG4-targeted CAR T cells demonstrated potent cytotoxicity and feasibility for clinical-scale mRNA-based manufacturing." (PMID 41516067, 2025). "The study preliminarily explored the role of CSPG4 in triggering the PANoptosis program and promoting the tumor progression of BLCA, and further validation based on experiments is required, which would be performed in future work." (PMID 40918470, 2025). "This demonstrated that administration of a murine anti-CSPG4 IgG1 mAb (clone 225.28) significantly reduced tumour size, along with altering the expression of melanogenesis- and metastasis-associated genes." (PMID 39409881, 2024). "Chondroitin sulfate proteoglycan 4 (CSPG4) is a cell surface proteoglycan released from pericytes to influence tumor angiogenesis." (PMID 39086395, 2024). "In this study, the deletion of CSPG4 reduced the spheroid formation and tumor burden in peritoneal metastasis." (PMID 38338902, 2024). "In the tumor tissues, mRNA expression of CSPG4 and CHST15 declined following treatment with exogenous ARSB (p < 0.001, two-sample t-test, two-tailed, unequal variance, n = 6)." (PMID 37813168, 2024). "The results showed that only CSPG4 was expressed at low levels in the tumor tissues, while the other three genes exhibited high levels of expression in the tumor tissues." (PMID 39659999, 2024).